RNU7-52P (RNA, U7 small nuclear 52 pseudogene)
Synonyms: U7.52
Gene: Small nuclear RNA gene on chromosome 17 (62,383,104 to 62,383,166, forward strand). Ensembl gene ENSG00000251981.
Homologues: Orthologues: macaque U7 (94% identical), pig U7 (84% identical). Paralogues in human: RNU7-35P (89% identical), RNU7-143P (87% identical), RNU7-160P (87% identical), RNU7-24P (87% identical), RNU7-2P (87% identical), RNU7-60P (87% identical), RNU7-11P (86% identical), RNU7-12P (86% identical), RNU7-3P (86% identical), RNU7-56P (86% identical), RNU7-7P (86% identical), U7 (86% identical), and 143 more.